TEF (TEF transcription factor, PAR bZIP family member)
Description:
Transcription factor that binds to and transactivates the TSHB promoter. Binds to a minimal DNA-binding sequence 5'- [TC][AG][AG]TTA[TC][AG]-3'.
Synonyms: KIAA1655
Tractability: Small molecule: a structure with a bound ligand is known.
Gene: Protein-coding gene on chromosome 22 (41,367,333 to 41,399,326, forward strand). Ensembl gene ENSG00000167074.
Subcellular location: Nucleus
Gene Ontology:
Molecular function: protein binding; sequence-specific double-stranded DNA binding; DNA-binding transcription factor activity, RNA polymerase II-specific; RNA polymerase II cis-regulatory region sequence-specific DNA binding; DNA-binding transcription factor activity; double-stranded DNA binding
Biological process: positive regulation of transcription by RNA polymerase II; regulation of transcription by RNA polymerase II; regulation of DNA-templated transcription
Cellular component: chromatin; nucleus
Genetic constraint (gnomAD): Loss-of-function variants: 3 observed, 19.95 expected, observed/expected ratio (o/e) 0.15, 90% interval 0.067 to 0.39. The upper end of that interval is the gene's LOEUF score, 0.39, which puts it in group 1 of 6, group 1 being the genes least tolerant of losing a copy. Missense variants: 296 observed, 389.47 expected, observed/expected ratio (o/e) 0.76, 90% interval 0.69 to 0.84. Synonymous variants: 180 observed, 170.03 expected, observed/expected ratio (o/e) 1.06, 90% interval 0.94 to 1.2.
Homologues: Orthologues: macaque TEF (100% identical), chimpanzee TEF (99% identical), rabbit TEF (98% identical), pig TEF (98% identical), mouse Tef (97% identical), rat Tef (88% identical), guinea pig TEF (86% identical), dog TEF (82% identical), tropical clawed frog tef (57% identical), zebrafish tefa (55% identical), zebrafish tefb (54% identical), Drosophila melanogaster Pdp1 (36% identical), and 3 more. Paralogues in human: HLF (50% identical), DBP (40% identical).
Diseases named in the same sentence as TEF in open-access papers:
TEF is named in the same sentence as 27 diseases in open-access papers, as found by Europe PMC text mining. Sharing a sentence is not in itself a finding about the gene and the disease. The quoted sentences say what the papers report.
bladder cancer (4 papers, 2019 to 2025). "In bladder cancer, upregulation of TEF expression significantly retarded bladder cancer cell growth by inhibiting the G1/S transition via regulating AKT/FOXOs signaling." (PMID 41394854, 2025). "TEF was previously reported to retard bladder cancer cell growth by inhibiting G1/S transition and regulating AKT/FOXOs signaling, which are both closely related to glycolysis/gluconeogenesis homeostasis." (PMID 37553601, 2023). "The mRNA levels of TEF in 408 bladder cancer (BC) samples from the Cancer Genome Atlas (TCGA) database were analysed in depth." (PMID 30515906, 2019).
depression (4 papers, 2009 to 2023). "In TEF, rs738499 was associated with unipolar depression; in a replication study, rs738499 was also associated with the QIDS-SR depression scale in the sleep clinic patient sample." (PMID 19166596, 2009). "More specifically, depression was significantly more common in PD patients carrying the TT genotype of TEF rs738499, suggesting that this polymorphism may represent a genetic risk factor for PD-related depressive symptoms." (PMID 37374342, 2023). "Interestingly, rs202637 is associated with PD (meta-GWAS p < 0.05) and TEF polymorphisms have been linked with depression and depression in PD specifically." (PMID 36325427, 2022). "The association of TEF rs738499 with unipolar depression may also prove reliable." (PMID 19166596, 2009). "A preliminary result associating TEF rs738499 with depression could not be confirmed in our expanded samples, despite an apparent replication in a group of Parkinson’s patients." (PMID 23521777, 2013). "Concerning PD depression, it has been indicated that TEF rs738499, but not CRY1 rs2287161 or CRY2 rs10838524 gene polymorphisms, were linked to depressive symptoms among PD patients in the Chinese population." (PMID 37374342, 2023). "TEF, CRY1, and CRY2 gene polymorphisms have been associated with depression risk in non-PD individuals." (PMID 37374342, 2023). "By stimulatory binding at D-box promoter sites, TEF may promote transcription of NR1D1, NR1D2, and the PER genes, actions which might be supposed to stimulate mania or counter depression." (PMID 19166596, 2009).
epilepsy (3 papers, 2011 to 2021). A brain disorder characterized by episodes of abnormally increased neuronal discharge resulting in transient episodes of sensory or motor neurological dysfunction, or psychic dysfunction. "First, circadian rhythm genes (BMAL1 and CLOCK), and their transcription factor complex, BMAL1–CLOCK, are known to influence the expression of other genes that are causally involved in epilepsy (for example, PAR DBP, TEF, and HLF)." (PMID 33192961, 2020). "Future studies will need to be done in order to establish an association between TEF or other PAR bZIP gene mutations and epilepsy or other neuronal disorders." (PMID 21347262, 2011).
cardiac hypertrophy (1 paper, 2014). "Vgl-4 (vestigial related factor 4) is a vital co-activator of the TEF (transcription enhancer family) and a marker of cardiac hypertrophy and was already significantly up-regulated by 4 weeks of age in R6/2 mice and as early as 8 months in HdhQ150." (PMID 25101683, 2014).
COVID-19 (1 paper, 2023). A disease caused by infection with severe acute respiratory syndrome coronavirus 2. "Among them, C3 population (high activity of OCT1 and CREB) decreases and C4 population (high activity of CEBP and TEF) increases during COVID-19 progression from healthy to moderate to severe." (PMID 36641532, 2023).
hyperthyroidism (1 paper, 2024). Overactivity of the thyroid gland resulting in overproduction of thyroid hormone and increased metabolic rate. "A high mRNA level of TEF was rapidly induced in hyperthyroidism." (PMID 38373887, 2024).
kidney tumor (1 paper, 2023). "Thus, we hypothesized that TEF was the main target of miR-4477b to suppress gluconeogenesis in kidney tumor cells." (PMID 37553601, 2023).
lung carcinoma (1 paper, 2024). "In contrast, the correlations between PER3, TEF, HLF and DBP are not altered in lung cancer." (PMID 39004631, 2024).
myeloma (1 paper, 2010). "In myeloma cells, the downregulation of TEF mRNA triggers an important Bik decrease, confirming the role of TEF in Bik transcription." (PMID 21063407, 2010).
porphyria (1 paper, 2022). Porphyria is a group of diseases in which substances called porphyrins build up, negatively affecting the skin or nervous system. "With the exception of ARNTL and TEF, all genes appeared significantly over-expressed in patients affected by all the tested types of porphyrias (both acute and cutaneous forms) with respect to controls." (PMID 36551954, 2022). "Interestingly, in all patients affected by both acute and cutaneous forms of porphyria, heme biosynthesis failure was associated with increased expression levels of the considered circadian genes when compared with the controls, except for ARNTL and TEF." (PMID 36551954, 2022).
prostate carcinoma (1 paper, 2017). A carcinoma that arises from epithelial cells of the prostate gland. "Moreover, 8 of these TFs (FOXJ2, GATA6, NFE2L1, NFIL3, PRRX2, TEF, EBF2 and ZBTB18) were found to be differentially expressed in this study making them not only candidate biomarkers of prostate cancer but also potential therapeutic targets." (PMID 28380430, 2017).
Tracheomalacia (1 paper, 2014). "Respiratory morbidity associated with EA ± TEF may be due to numerous players intrinsically related to the malformation itself or the surgical treatment (with or without complications), and has been often ascribed to associated disorders like tracheomalacia and GER." (PMID 24829898, 2014).
tumor (11 papers, 2011 to 2023). "TEF in 22q13.2 is an apoptotic regulator of hematopoietic progenitors with tumor promoting effects mediated by inhibition of G1/S cell cycle transition and Akt/FOXO signaling." (PMID 33109261, 2020). "Western blot analysis confirmed that TEF protein remained high in tumours generated from TEF‐overexpressing HT‐1376 cells, while TEF proteins remained low in tumours generated from TEF‐silenced HT‐1376 cells." (PMID 30515906, 2019). "The RNA expression of TEF was higher in early‐stage tumours (stages I‐II) and was lower in advanced‐stage tumours (stages III‐IV, P < 0.01)." (PMID 30515906, 2019). "Moreover, restoring gluconeogenesis by overexpressing PCK1 or TEF through miR-4477b inhibition significantly inhibited tumor cell proliferation, colony formation, and induced cell apoptosis in vitro." (PMID 37553601, 2023). "The Hippo tumor suppressor pathway regulates tissue growth in Drosophila by restricting the activity of the transcriptional coactivator Yorkie (Yki), which normally complexes with the TEF/TEAD family DNA-binding transcription factor Scalloped (Sd) to drive the expression of growth-promoting genes." (PMID 30901309, 2019).
cancer (9 papers, 2010 to 2026). A tumor composed of atypical neoplastic, often pleomorphic cells that invade other tissues. "Moreover, upregulation of TEF expression substantially retards cancer cell growth by inhibiting the G1/S transition via regulating AKT/FOXOs signaling." (PMID 38575629, 2024). "The key difference between the core clock in these cancers and healthy tissue was a significant delay in the peak expression times of core clock genes NR1D2, PER2, TEF and DEC1." (PMID 40424435, 2025). "For instance, CLOCK was selectively expressed in ER+ cancer, whereas PER1 and TEF were highly expressed in both ER+ and HER+, and finally PER3 was expressed in HER2+ and TNBC." (PMID 39201344, 2024). "Among 7912 samples across 18 cancer types, we interestingly observed that the majority of the clock control gene, such as HLF, KLF10, FBXL3, TEF, RORs (RORA, RORB, RORC), and NR1D2, are down-regulated in a wide range of cancers." (PMID 36895015, 2023). "Despite TEF expression, some cell lines do not express Bik, probably due to a potential deletion of Bik at 22q13.2, as frequently described in other cancers." (PMID 21063407, 2010).
infection (1 paper, 2021). The state of being infected such as from the introduction of a foreign agent such as serum, vaccine, antigenic substance or organism. "Of these, CD44, KDM1B, FKBP4, TEF, SYT4, SATB1 and PLCD1 are reported to be involved in the inflammatory reaction; for the remaining ten genes, there have been no reports concerning inflammation or infection." (PMID 34046191, 2021).
TEF also shares sentences with these, for which no sentence is quoted: asthma (2 papers); breast carcinoma (2); allergic disease (1); bladder tumour (1); degenerative diseases (1); liver cancer (1); lymphoma (1); Parkinson’s (1); psychiatric disorder (1); skin cutaneous melanoma (1); squamous cell carcinoma (1); vitiligo (1).